IL6 (interleukin 6)
Diseases named in the same sentence as IL6 in open-access papers (continued):
Sharing a sentence is not in itself a finding about the gene and the disease.
infection (continued). "Additionally, co-infections involving IAV and SARS-CoV-2 exhibited cytokine dynamics dependent on the infection sequence, with elevated TNF-α, IL-6, and IFN-β levels following sequential infections, particularly when SARS-CoV-2 preceded IAV." (PMID 40005506, 2025). "Upon infection, alveolar epithelial cells activate pattern recognition receptors (PRRs), including retinoic acid-inducible gene-I (RIG-I), MDA5 and TLR3, and respond rapidly by releasing type I and III IFNs, IL-6 and chemokines such as CXCL10." (PMID 40969755, 2025). "This study primarily investigates the correlation between inflammatory cytokines TNF-α, IL-6, and IFN-γ with DFI and further analyzes their relationship with infection severity, aiming to provide clinical guidance for early intervention, thereby improving patient prognosis and quality of life." (PMID 40677522, 2025). "Third, although inflammatory markers such as CRP or IL-6 were not available for the entire cohort, all patients with documented clinical or laboratory evidence of infection were excluded from the latter." (PMID 40970059, 2025). "In addition to reducing Infection rates, the significant reduction In proinflammatory cytokines (TNF-α, IL-1, IL-6) In the research group provides further evidence of the efficacy of the combined HPNS and probiotic Intervention." (PMID 40951884, 2025). "The results showed that the polyclonal antibody not only effectively reduced the adhesion rate of MP cells to A549 cells but also significantly inhibited the expression of the key inflammatory factors IL-6 and TNF-α in Beas-2b cells and in model mice after infection." (PMID 41156647, 2025). "In addition, 25–100 mg/kg baicalin reduced the mRNA expression levels of IL-1β, IL-6, IL-8, IL-18, TNF-α, and COX-2 in the spleen compared to the infection group (p < 0.05)." (PMID 40427533, 2025). "The RNA of Il6 and Ptgs2 detected by qPCR show similar trends to the transcriptome data, although the RNA of Tnfa and Il1b showed constant elevation post infection, which was not completely consistent with the transcriptome data." (PMID 38992966, 2025). "Stimulation of both primary monocytes and THP-1 reporter cell lines with SARS-CoV-2-derived ssRNA led to profound upregulation of all measured cytokine genes, while primary monocytes increased TNF, IL1B and IL6 and decreased CXCL8 expression upon infection with replication-competent SARS-CoV-2." (PMID 39963132, 2025). "Therefore, the levels of TNF-α, IL-6, IFN-γ, and CCL4 in serum were measured at 4, 24, and 48 h post infection." (PMID 40872776, 2025). "However, we identified four chemokines and cytokines that correlate with virulence in a murine in vivo infection model: MCP-1, IL-6, IL-10 and IFN-γ." (PMID 40587585, 2025). "As a central mediator of the acute-phase response, IL-6 promotes CRP synthesis in hepatocytes, enhances neutrophil activation, and regulates the early inflammatory cascade by mobilizing immune cells to the site of infection." (PMID 41018059, 2025). "Inflammation is a critical host response to infection, mediated by immune cells such as monocytes and macrophages, which release proinflammatory cytokines (e.g., tumor necrosis factor α (TNF-α), interleukins (IL-1β, IL-6, and IL-8)) upon pathogen recognition." (PMID 40564288, 2025). "IL-6 hyporesponsiveness, as seen in our study, may affect the ability of children with SNI to respond adequately to infection." (PMID 40661891, 2025). "IL-6 displayed moderate sensitivity but limited specificity, likely reflecting cytokine release triggered by surgical trauma rather than infection alone." (PMID 41281040, 2025). "Therefore further research investigating the prognostic value of IL-6 and CRP relative to other predictors of postoperative infection is needed to draw final conclusions on the clinical utility of either biomarker." (PMID 40549692, 2025).
infection (continued). "Recent evidence has identified IL-6, IL-8, and IL-10, alongside acute-phase reactants such as C-reactive protein (CRP) and procalcitonin (PCT), as promising biomarkers for early infection detection in neutropenic patients, supporting timely and targeted therapeutic interventions." (PMID 40647525, 2025). "In addition, the ΔrfbBΔrffG strain induced lesser amounts of pro-inflammatory cytokines such as TNF-α, IL6, and IFN-γ than the WT strain in both the oral and the i.p. modes of infection." (PMID 40469742, 2025). "The augment of IL-6 and MIF induced by BRP and 7-O-methylvestitol plays a relevant role in controlling the T. gondii proliferation since both cytokines are widely known to reduce the infections in several cell types, including trophoblast." (PMID 40871442, 2025). "We found that concentrations of soluble TNFR2 and sCD163 decreased significantly during follow-up in those with HCV mono-infection; there were no changes in the concentrations of sTNFR1 or IL-6 in either the HCV mono-infected group or the reference group." (PMID 41394829, 2025). "At 10 and 5%, the digested CFS in MRS significantly countered the IL-6 increase upon infection (p < 0.01), and the addition of vitamin D did not improve this outcome." (PMID 40351306, 2025). "Research indicates that approximately half of patients with community-acquired acute hepatitis C can spontaneously clear the virus, and significantly higher levels of IL-1β, IL-1RA, IL-6, IFN-γ, and FGF-2 were detected in the serum of patients achieving self-limited infection." (PMID 40934209, 2025). "Infection studies using recombinant Msmeg strains expressing Mtb PE18 and PPE26 proteins confirmed these findings, demonstrating enhanced production of proinflammatory cytokines such as TNFα, IL6, and IL12." (PMID 39949767, 2025). "Blockade of IL-6 trans-signaling can be achieved at comparably low therapeutic concentrations and does not appear to hamper infection control or IL-6-mediated acute-phase reaction in preclinical models." (PMID 39857830, 2025). "Consistent with the lack of effect on BR15 infection, AbII treatment did not significantly alter the levels of IL-1β, IL-6, IL-10, CCL2 (MCP-1), CCL5 (RANTES), or CXCL8 (IL-8) in BR15-infected cells." (PMID 40732762, 2025). "LC patients showed slightly increased secretion of IL-1β, IL-6, TNF-α, GM-CSF and G-CSF, raising the possibility that other pro-inflammatory cytokines may also be disturbed, as observed by others 8 months after infection." (PMID 40566632, 2025). "At 72 hours post-infection, protein levels of IL-17, IFN-γ, T-bet, RORγt, and IL-6 were significantly decreased, whereas TGF-β, GATA-3, IL-4, and FoxP3 protein expression was significantly upregulated in the Pm_OMVs-infected group compared to the Pm group (P < 0.01)." (PMID 41306977, 2025). "Additionally, PRV-GXLB-2013 infection induced a highly significant upregulation in mRNA expressions of TNF-α, IL-1β, IL-6, NF-κB p65, RIP3, and MLKL (p < 0.01), alongside a pronounced downregulation of IκBα (p < 0.01), in both brain tissues and C8-D1A cells." (PMID 40732040, 2025). "Studies have shown that dysregulated proinflammatory cytokines such as IFNs, IL6, and TNF may compromise viral clearance while minimizing tissue damage, creating a condition that supports persistent infection despite low infectivity." (PMID 40649996, 2025). "However, the secretion of TNF-α, IL-6, and CXCL-8/IL-8 by DENV-2-infected MDMs occurred at late stages of infection, suggesting that the translation and/or secretion of these inflammatory factors are delayed in DENV-2 replicative cycle." (PMID 40934228, 2025). "Although cytokine dosage confirmed that Delta infection did not induce secretion of IL-6 or RANTES throughout the time-course of infection, it revealed that it induced significant secretion of IL-8 at 72 and 96 hpi." (PMID 40142465, 2025).
infection (continued). "In preterm infants, particularly those born before 32 weeks of gestation, IL-6 levels tend to be higher even in the absence of confirmed infection, largely due to intrauterine inflammation and conditions such as PPROM." (PMID 41302151, 2025). "This infection resulted in an increase in IL-6 and a non-significant increase in IFN-α and a significant increase in IL-8 (key mediators in the immune system) after combined Hyp/PEN treatment, but this was reversed by PDT." (PMID 41373828, 2025). "We observed that decidualization increases IL-6 and IL-8 levels, while infection with SARS-CoV-2 did not further augment these cytokines." (PMID 39666439, 2025). "Additionally, cytokine analysis revealed that IL-6 and TNF-α levels were elevated in the infection group but significantly reduced in the APR treatment group within 24 h, emphasizing the immediate anti-inflammatory effects of APR." (PMID 40284856, 2025). "Across these infections, IL-6 mRNA expression and protein secretion were consistently reduced in TBC1D9-KO cells compared to WT controls (p < 0.05), indicating that TBC1D9 regulates IL-6 responses to various bacterial pathogens." (PMID 41306588, 2025). "The expression of p72 in macrophages containing inclusion bodies, together with the isolation results from the LVI–HVI1 subgroup, indicates that the observed necrotic lesions are a direct consequence of Arm07 infection, mediated by the secretion of TNF‐α, IL‐1, and IL‐6." (PMID 41395245, 2025). "It is interesting that the pulmonary IL-6 level, but not the IL-1β or TNFα levels, significantly decreased in mice deficient in caspase-11 or NLRP3 upon infection." (PMID 40034692, 2025). "Indeed, similar to T-cell activation, the plasma levels of pro-inflammatory cytokines (IFN-γ, IL-6, IL-8, TNF, and MIP-1β) were higher in patients with VL/HIV co-infection than in those with HIV or VL mono-infection and healthy individuals." (PMID 40145085, 2025). "In control infected pAMs, no changes in the expressions of IL-6, or IL-27 were detected in comparison to non-infected cells both at 6 and 24 h post-infection." (PMID 41155369, 2025). "At the sites of infection, an increased number of CD8+ T cells, along with heightened expression of pro-inflammatory cytokines, e.g., Il-6 and TNFα, may have contributed to tissue damage." (PMID 41150440, 2025). "That is, our MR findings should be interpreted as showing that IL-6 activity is causally predicted to increase the odds of development of infection, and not that IL-6 activity during an episode of infection is thereby pathological." (PMID 40819633, 2025). "In terms of mRNA expression, the cytokines Interleukin 6 (IL-6), Interleukin 8 (IL-8), Interferon Beta (IFN-β), Interferon Gamma (IFN-γ), and Tumor Necrosis Factor Alpha (TNF-α) were significantly upregulated (P < 0.001) to varying degrees following infection." (PMID 40642060, 2025). "Additionally, another study has shown that older children, compared to their younger counterparts at the same stage of infection, have reduced levels of pro-inflammatory cytokines like TNF-α, IL-2, and IL-6, as well as Th1-biased chemokines." (PMID 41194029, 2025). "When L3 CFS was used, it was observed that the MRS-produced one at 20% v/v ration, both with and without vitamin D, did not decrease IL-6 production upon FaDu infection, but it significantly increased it compared to the infection control (p < 0.05)." (PMID 40351306, 2025). "The distinctive elevation of serum HBP, TNF-α, IL-6, and CRP levels in children with severe adenovirus pneumonia as well as those with poor prognosis underscored the central role of inflammatory pathways in the pathogenesis and prognosis of this infection." (PMID 40963970, 2025). "Both compounds also significantly reduced IL-6, IL-8, and TNFα release by hMDM in both infection models, regardless of differences between ATCC 33277 and W83 Pg strains." (PMID 41221328, 2025).
infection (continued). "Additionally, a mouse infection model was established using P. aeruginosa PAO1 to investigate the impact of RmmLII on the production of inflammatory cytokines IL-1β, IL-6, and TNF-α, as well as mouse survival rates." (PMID 40170927, 2025). "In conclusion, early postoperative plasma IL-6 and CRP concentrations are independently associated with subsequent infection risk, although neither biomarker improved prognostic classification by a simple prediction model using readily available clinical data." (PMID 40549692, 2025). "Considering that the cells were only exposed to the bacteria for 3 h, the PA isolates would be considered as early infections rather than chronic, explaining why the IL-6 response was low in HNECs infected with PA isolates alone." (PMID 40788668, 2025). "Infection-specific biomarkers, such as procalcitonin or IL-6, were not measured, limiting mechanistic interpretation." (PMID 41008500, 2025). "IL-6 plays a crucial role in the progression of VL, exhibiting various effects, such as inducing immunosuppression in the liver of the infected host, increasing hypergammaglobulinemia, and inhibiting TNF-α production during the early stage of infection." (PMID 39670465, 2025). "Polarized M1 THP-1 macrophages were resistant to TcpC’s influence on IL-1β but not TNFα or IL-6 secretion during an infection with CFT073." (PMID 41310197, 2025). "The progression to multi‐organ failure, along with markedly elevated IL‐6 levels and the absence of a confirmed infection, further supported an immune‐mediated process, confirming the diagnosis of CRS." (PMID 40391237, 2025). "Systemic inflammation, evaluated through the expression of inflammatory cytokines like IL-1B, IL-6, IL-8, IL-15, and TNF-a, is upregulated in the acute phase of TBI and impacts clinical outcomes such as mortality, the occurrence of infections in the acute and subacute period, and functionality." (PMID 40713822, 2025). "For example, compared with infection with low pathogenicity influenza virus (IAV) strains, lethal IAV strain infection preferentially upregulated TLR3 to a greater extent, which induced dysregulation of cytokines such as IL-6 and TNF-α and enhanced viral replication." (PMID 41221396, 2025). "Studies have shown that if the infection is not completely cleared from the body, it can lead to the continuous production of pro-inflammatory cytokines such as IL-1β, IL-6, IL-8, and TNF-α, which can limit the formation of granulation tissue and microvessels." (PMID 40529353, 2025). "BMDC infection with M.tb CDC1551, measured TNF-α and IL-6 levels, and CD4+/CD8+ T cells in MLNS." (PMID 41256867, 2025). "Our experimental infection model, which utilized the infection of A549 NTC cells as controls, corroborated these findings, displaying intracellular bacterial survival, low levels of cell death, and low secretion of the cytokine IL-6." (PMID 40861495, 2025). "Western blot results demonstrated that in IBV-infected CEK cells, baicalin significantly promoted the protein expression of IL-1β, IL-6, TNF-α, TLR7, and MyD88 at 24 h post-infection (hpi), whereas it markedly suppressed the expression of these factors at 48 hpi." (PMID 41375455, 2025). "Infection of THP-1 cells with MAP upregulated MCT4 expression (2 folds) and resulted in a significant increase in lactate export (1.3 folds), TNFα (13.8 folds), and IL-6 (1.3) via TLR2 activation." (PMID 40297589, 2025). "LAP inhibition did not affect proinflammatory cytokine secretion as the levels of IL-1β, TNF and IL-6 were not affected 24 hours post-infection of macrophages pretreated with SAR405 and GSK2795039, respectively." (PMID 40395986, 2025). "We tested to see if the IL-6 and CRP values were sensitive to infection." (PMID 40242671, 2025). "Regarding Jar treatment, this SVMP strongly downmodulated IL-6 release by HeLa cells in the presence or absence of infection when compared to the uninfected/untreated or infected/untreated cells (*** p < 0.001)." (PMID 39998112, 2025).
infection (continued). "Levels of IL-6 did not significantly differ between treatment groups 3 h post-infection nor 4 days post-infection." (PMID 41155292, 2025). "Yet following treatment, the rates of infection were significantly lower in these patients compared with non-IL-6 bDMARD-treated patients [difference 10.5% (95% CI 3.7, 19)]." (PMID 39698233, 2025). "Moreover, infection with SFV/IFNγ and SFV/TNFα upregulated the amount of IL-6, CCL4 and CXCL11 (p < 0.05)." (PMID 40547518, 2025). "Intestinal perforation or serious infections, which were a concern in patients treated with other anti-IL-6 agents for a similar period, did not occur with olamkicept, although the study was not designed to assess safety." (PMID 39857830, 2025). "For the TRY-digested L3 CFS, the 20% concentration did not effectively reduce IL-6 production upon infection regardless of vitamin D presence." (PMID 40351306, 2025). "infection did not change the levels of cytokines interleukin 1β (IL-1β), IL-6, IL-10, interferon gamma (IFN-γ), and tumor necrosis factor alpha (TNF-α)." (PMID 40302747, 2025). "Further validation via Western blot analysis indicated that protein expression levels of IFN-γ, IL-4, IL-6, IL-17, TGF-β, GATA-3, T-bet, RORγt, and FoxP3 were significantly increased in the Pm_OMVs-infected group at 24 hours post-infection relative to the Pm group (P < 0.01)." (PMID 41306977, 2025). "However, comparable levels of TNF, IL-6, IL-10, CXCL1, CCL3, GM-CSF, and G-CSF were observed upon CRWT and CRM12 infection." (PMID 40599135, 2025). "Although IL-6 did not outperform CRP as an early predictor for postoperative infection in our study, it would be premature to conclude that the predictive performance of both biomarkers is equal." (PMID 40549692, 2025). "The favorable outcomes observed in the present study can be explained as Losartan-only and Losartan + Lisinopril combination treatments resulted in marked reductions in the levels of the pro-inflammatory cytokines IL-6 and TNF-α following infection by SARS-CoV-2." (PMID 40868984, 2025). "Furthermore, the levels of CXCL1, IL-6, and TNF-α in the culture supernatants were increased by EV-A71 infection." (PMID 39679722, 2025). "The results of this study indicate that serum levels of TNF-α, IL-6, and IFN-γ were significantly elevated in DFI patients compared to diabetic foot patients without infection, and their levels positively correlated with infection severity." (PMID 40677522, 2025). "Additionally, IL-6 and IL-8 secretion increased significantly in a dose-dependent manner, starting from day 1 and day 3, respectively, following rgDENV2-NS1-K272R infection." (PMID 39972477, 2025). "Both ME49 and CK4 infection lead to similarly increased levels of IL-6 in early chronicity, when compared to the non-infected animals (ME49 P = 0·002; CK4 P = 0·0004)." (PMID 40223760, 2025). "Our results demonstrated that HUVEC not only exhibit a higher infection rate than HBMEC but also display a more pro-inflammatory transcriptional profile, with increased expression of interleukin-6 (IL6), interleukin-8 (IL8), and monocyte chemotactic protein-1 (MCP1) following infection." (PMID 40141288, 2025). "Upon tissue damage, infection, or other stimuli, immune cells will generate IL-6, such as macrophages, monocytes, and non-immune cells including endothelial cells, mesenchymal cells, and fibroblasts." (PMID 39858184, 2025). "Interleukin-1 beta (IL-1β), interleukin-6 (IL-6), and serum amyloid A (SAA) are well-known pro-inflammatory cascades, exhibiting high expression levels in rainbow trout (Oncorhynchus mykiss) during Ich infections." (PMID 40509043, 2025). "IL-6 did not appear to be useful in the differentiation of neonates with infections and those with non-infectious pathological conditions." (PMID 40171168, 2025).